MMP10 (matrix metallopeptidase 10)
Description:
Can degrade fibronectin, gelatins of type I, III, IV, and V; weakly collagens III, IV, and V. Activates procollagenase.
Synonyms: SL-2; STMY2
Tractability: Small molecule: a structure with a bound ligand is known; a high-quality ligand is known; it has a high-quality binding pocket; it belongs to a druggable protein family. Antibody: UniProt places it where antibodies can reach, with high confidence; its Gene Ontology location is reachable by antibodies, with high confidence; UniProt predicts a signal peptide or a membrane-spanning region; the Human Protein Atlas places it where antibodies can reach. PROTAC: a small molecule that binds it is known.
Target class: Metallo protease; Metallo protease M10A subfamily; Metallo protease MAM clan; Protease; Enzyme
Gene: Protein-coding gene on chromosome 11 (102,770,502 to 102,780,628, reverse strand). Ensembl gene ENSG00000166670.
Subcellular location: Secreted, extracellular space, extracellular matrix
Subcellular location (Human Protein Atlas): Cytosol; Plasma membrane; Predicted to be secreted
Pathways (Reactome):
Extracellular matrix organization: Activation of Matrix Metalloproteinases; Collagen degradation; Degradation of the extracellular matrix
Signal Transduction: MAPK6/MAPK4 signaling
Gene Ontology:
Molecular function: metalloendopeptidase activity; serine-type endopeptidase activity; zinc ion binding; endopeptidase activity; metallopeptidase activity
Biological process: collagen catabolic process; extracellular matrix disassembly; extracellular matrix organization; proteolysis
Cellular component: extracellular matrix; extracellular region
Genetic constraint (gnomAD): Loss-of-function variants: 45 observed, 45.93 expected, observed/expected ratio (o/e) 0.98, 90% interval 0.77 to 1.26. The upper end of that interval is the gene's LOEUF score, 1.26, which puts it in group 5 of 6, group 1 being the genes least tolerant of losing a copy. Missense variants: 562 observed, 538.55 expected, observed/expected ratio (o/e) 1.04, 90% interval 0.97 to 1.12. Synonymous variants: 212 observed, 196.81 expected, observed/expected ratio (o/e) 1.08, 90% interval 0.96 to 1.21.
Homologues: Orthologues: chimpanzee MMP10 (99% identical), macaque MMP10 (93% identical), rabbit MMP10 (83% identical), guinea pig MMP10 (80% identical), zebrafish mmp13b (48% identical), tropical clawed frog mmp8 (48% identical), zebrafish mmp30 (42% identical), zebrafish mmp25b (34% identical), Drosophila melanogaster Mmp1 (34% identical), zebrafish mmp25a (33% identical), Caenorhabditis elegans zmp-3 (27% identical), Caenorhabditis elegans zmp-1 (25% identical), and 7 more. Paralogues in human: MMP3 (78% identical), MMP1 (51% identical), MMP27 (51% identical), MMP8 (50% identical), MMP12 (49% identical), MMP13 (49% identical), MMP20 (45% identical), MMP2 (43% identical), MMP9 (38% identical), MMP14 (38% identical), MMP15 (38% identical), MMP16 (37% identical), and 11 more.
Diseases named in the same sentence as MMP10 in open-access papers:
MMP10 is named in the same sentence as 239 diseases in open-access papers, as found by Europe PMC text mining. Sharing a sentence is not in itself a finding about the gene and the disease. The quoted sentences say what the papers report.
breast carcinoma (29 papers, 2009 to 2025). "MMP-10 expression has been associated with invasion and metastasis of pancreatic, cervical, bladder, colorectal, gastric, lung, and breast cancers." (PMID 28337194, 2017). "In order to validate results from the microarray analysis, we chose MMP10, which has been previously implicated in metastasis in breast cancer cells as well as in other cancer types." (PMID 27351228, 2016). "The aim of the study was to evaluate if plasma levels of selected metalloproteinases (MMPs) (stromelysin-1 (MMP-3) and stromelysin-10 (MMP-10)) and cancer antigen 15-3 (CA 15-3) used separately and in combination demonstrated diagnostic usefulness in breast cancer (BC)." (PMID 33371324, 2020). "Notably, there is a significant association in the expression of P-Rex1 and MMP10 in human luminal breast cancer, and their co-expression is indicative of poor prognosis." (PMID 27351228, 2016). "Nevertheless, in the course of different cancers such as breast cancer, higher levels of MMP-10 were found in the cancer group compared to women with benign lesions and healthy women." (PMID 41007705, 2025). "In conclusion, our findings demonstrated that exosomal SNHG12 regulates HUVEC angiogenesis to promote breast cancer progression by interacting with PBRM1 to target MMP10." (PMID 38833118, 2024). "We found that both Mmp9 and Mmp10 genes are upregulated in primary tumors of human breast cancer patients compared to normal solid tissue." (PMID 36612044, 2022). "Induction of an EMT program in breast cancer cells causes MMP production, and increased expression of MMP3, MMP10, and MMP13 was observed upon TGF-β stimulation of human breast cancer cell lines." (PMID 30356678, 2018). "Future studies in our laboratory are aimed at dissecting potential roles for MMP10 and other relevant genes identified in our analysis in breast cancer progression." (PMID 27351228, 2016). "Our results showing that SDF-1 activate Rac1 and induce MMP10 in breast cancer cells are in line with this finding." (PMID 27351228, 2016). "This resulted in the identification of two upregulated genes (DPEP1 and MMP11) as mutated in colon cancer and another three protease genes mutated in breast cancer (TMPRSS3, ADAM12 and MMP10)." (PMID 24243807, 2013). "In contrast, Gadd45a functions to promote Myc-driven breast cancer by negatively regulating MMP10 via GSK3B/B-catenin signaling, resulting in increased tumor vascularization and growth." (PMID 23706118, 2013). "Although the amount of MMP-10 (stromelysin 2) on mRNA level was equal in all analyzed samples, expression of its pro and active protein form was significantly higher in breast cancer samples." (PMID 19531263, 2009). "A study conducted on MCF-7 cell lines and intact uterus rats demonstrated that trilostane can up-regulate β-estrogen receptor expression and suppress specific estrogen-regulated genes, such as MMP-10, suggesting its potential in managing tamoxifen-resistant breast cancer." (PMID 39943185, 2025). "Likewise, HCMV IL-10 exposed MCF-7 human breast cancer cells showed a significant up-regulation of matrix metalloproteinase-10 (MMP-10) gene expression, thus promoting excessive proliferation and tissue invasion." (PMID 33937031, 2021). "Indeed, ERK has been shown to be a downstream effector of P-Rex1 in breast cancer cells and mediates MMP10 induction in other cell types." (PMID 27351228, 2016). "Therefore, consistent with the requirement of P-Rex1 for MMP10 induction, these results indicate that in breast cancer cells MMP10 expression is regulated by Rac1 activation." (PMID 27351228, 2016). "The significant association between PREX1 and MMP10 expression in luminal tumors, together with the poor prognosis found in luminal breast cancer patients with high PREX1 and MMP10 expression, suggest a causal relationship with disease progression that deserves to be fully explored." (PMID 27351228, 2016).
breast carcinoma (continued). "Moreover, a role for MMP10 has been proposed in MCF-7 breast cancer cells via regulation of the BAD protein." (PMID 27351228, 2016). "We demonstrated that SNHG12 was highly expressed in both breast cancer cells and their secreted exosomes, promoting HUVEC angiogenesis and tumor progression via PBRM1 and MMP10." (PMID 38833118, 2024). "For the matrix degradome, MMP1, MMP2, MMP10 and MMP14 showed trends of progressive upregulation with increasing metastatic potential in lung fibroblasts exposed to secreted factors from breast cancer cells." (PMID 37903851, 2023). "In breast cancer, MEF2A is activated by TGF-β and mediates TGF-β-induced breast cancer metastasis by upregulating MMP10." (PMID 33863999, 2021). "Several top up-regulated genes were associated with motility, adhesion, invasiveness, and metastasis in breast cancer or other cancers, such as GBP1, ITGB6, ITGA2, and matrix metalloproteases MMP10 and MMP1." (PMID 27351228, 2016). "Luminal A breast cancer patients with high PREX1 levels from which follow-up data was available were divided into two groups, low MMP10 and high MMP10 levels, based on the median expression values." (PMID 27351228, 2016). "Analysis revealed a strong positive correlation between Mmp10 expression and metastatic potential in human NSCLC, colorectal cancer, melanoma, breast cancer, renal cell carcinoma and prostate cancer." (PMID 22545096, 2012). "In breast cancer (BC), MEF2A induced tumour metastasis by affecting MMP10 expression." (PMID 37859585, 2023). "Up till now, studies on relationship between MMP-10 and prognosis of breast cancer was not available." (PMID 37188722, 2023).
atherosclerosis (19 papers, 2007 to 2025). A disease characterized by the build-up of fatty material and calcium deposition in the arterial wall resulting in partial or complete occlusion of the arterial lumen. "Elevated MMP-10 levels have been linked to diseases such as atherosclerosis, chronic kidney disease, and diabetes." (PMID 40278353, 2025). "Dysregulation of MMP-10 is implicated in the pathogenesis of various disorders including kidney diseases, tumorigenesis, atherosclerosis, and cardiovascular diseases." (PMID 35216251, 2022). "Elevated levels of MMP-10 were independently associated with the severity of atherosclerosis in patients with chronic kidney disease (CKD), and also associated with nephropathy in patients with type 1 diabetes." (PMID 31805809, 2020). "Recently, we demonstrated that MMP-10 (stromelysin-2) is associated with inflammation and subclinical atherosclerosis, and is also present in atherosclerotic lesions." (PMID 19690647, 2007). "Furthermore, in patients with CKD serum, MMP-10 concentrations were associated with atherosclerosis severity." (PMID 36079742, 2022). "Notably, MMP10 has also been implicated in the pathophysiology of atherosclerosis and diabetic retinopathy." (PMID 35884862, 2022). "In fact, increased plasma levels of MMP10 are associated with more severe atherosclerosis." (PMID 35884862, 2022). "Finally, our group has recently demonstrated a causal role of matrix metalloproteinase-10 (MMP-10) in atherosclerosis progression, macrophage infiltration and plaque calcification, using a double knock-out (2KO) mouse model (Apoe-/-Mmp10-/-)." (PMID 34062730, 2021). "Recently, our group and others have confirmed the relevant role of MMP-10 in the pathophysiology of atherosclerosis." (PMID 39456453, 2024). "Thus, the p.L245P variant in MMP10 may influence the pathogenesis of atherosclerosis in families with premature myocardial infarction by altering protein - protein interactions, macrophage adhesion and migration, and expression of pro-inflammatory chemokines, which may increase plaque rupture." (PMID 38806571, 2024). "Increased serum MMP-10 levels were connected with increased carotid intima–media thickness, atherosclerotic plaques, and inflammatory markers in patients with preclinical atherosclerosis." (PMID 32486345, 2020). "The presence of higher circulating levels of MMP-1 and MMP-10 in patients with carotid stenosis compared to healthy controls is in line with previous studies, highlighting the relationship between atherosclerosis and MMPs." (PMID 32101136, 2020). "Additionally, MMP-10 serum levels correlated with coronary calcification in subjects with subclinical atherosclerosis." (PMID 39456453, 2024). "Moreover, in human plasma, MMP-10 levels correlate with plaque calcification in patients with subclinical atherosclerosis." (PMID 39456453, 2024). "Additionally, plentiful studies suggest that MMP-10 has the potential to drive the progression of atherosclerosis and plays a role in vascular remodeling." (PMID 35216251, 2022). "Measurement of cytokines and proteases in the supernatants of HAoSMCs confirmed that inflammatory mediators, such as CXCL8, IL-6, IL-1β, and IL-1α and proteases, such as MMP-10 [role in atherosclerosis and vascular calcification], were produced and released by HAoSMCs upon aging in vitro." (PMID 34313809, 2021). "In addition, MMP-10 expression is induced by CRP in human endothelial cells and both parameters positively correlated with subclinical atherosclerosis in asymptomatic subjects with CV risk factors." (PMID 34062730, 2021). "Furthermore, studies in subjects with subclinical atherosclerosis showed a correlation between MMP-10 serum activity and the degree of coronary calcification." (PMID 32486345, 2020).
atherosclerosis (continued). "FLI1 regulates the expression of metalloproteases (MMP-1, MMP-3, and MMP-10) and the pro-inflammatory cytokine IL-10; therefore, during chronic inflammatory conditions, such as AR and atherosclerosis, FLI1 down-regulation could attenuate tissue damage associated with inflammatory responses." (PMID 39767648, 2024). "Indeed, the serum MMP-10 level is independently associated with carotid atherosclerosis, consistent with the notion that circulating MMP-10 level is an independent risk factor for atherosclerosis in CKD patients." (PMID 35216251, 2022). "In turn, MMP-10 expression is triggered by inflammatory stimuli present in chronic kidney disease (CKD), diabetes and atherosclerosis." (PMID 36079742, 2022). "Mediators involved in atherosclerosis (CX3CL1/fractalkine, CCL8, M-CSF, CXCL5, CCL4, HGF), tissue remodeling (MMP-12, MMP-1, MMP-10) and angiogenesis (VEGF-A) were also increased in AD." (PMID 28821884, 2017). "Regardless, we demonstrated that a characteristic stimulus of numerous cardiovascular diseases, including arterial hypertension and atherosclerosis, could promote ECM remodeling through the NOX5/MMP-10 axis." (PMID 39456453, 2024). "It was recently suggested that MMP-10 plays a role in the development of atherosclerosis, and in vitro studies found increased MMP-10 levels after infective stimulation of human and mice airway epithelial cells; however, no studies assessing MMP-10 levels have been reported in sepsis." (PMID 19799791, 2009).
lung carcinoma (19 papers, 2005 to 2021). "Some studies have implicated MMP10 in colon and lung cancers." (PMID 34301206, 2021). "The 10 most highly correlated signatures associated with high Mmp10 in lung cancer." (PMID 22022614, 2011). "We conclude that Mmp10 plays an important role in lung tumor initiation via maintenance of a highly tumorigenic, cancer-initiating, stem-like cell population, and that Mmp10 expression is associated with stem-like, highly metastatic genotypes in human lung cancers." (PMID 22022614, 2011). "In addition, MMP10 has been implicated in lung cancer initiation driven by oncogenic K-Ras." (PMID 27351228, 2016). "Our finding that Mmp10 is highly expressed in lung cancer-initiating BASCs, and is associated with the CSC genotype in human lung tumors suggests that Mmp10 may promote both CSC maintenance and metastatic potential through its role in CSC proliferation and metastatic behavior." (PMID 22022614, 2011). "Mmp10 is required for the growth of human lung cancer cells and for their inversion properties in vitro and in vivo." (PMID 30060526, 2018). "Studies carried out on murine lung cancer stem cells have led to identify Matrix Metalloproteinase 10 (Mmp 10) as a gene highly expressed in these cells and playing an important role in tumor initiation and maintenance." (PMID 30060526, 2018). "According to these observations it was suggested a direct role of Mmp10 in the maintenance of lung cancer stem cells." (PMID 30060526, 2018). "Higher MMP10 expression has been reported in lung cancer, head and neck cancer, oral cavity cancer, esophagus cancer, and cervical tumors." (PMID 28947680, 2017). "MMP10 is expressed in various types of cancers including esophageal cancer, lymphoma, head and neck cancer and lung cancer." (PMID 27072580, 2016). "MMP10 was reported to have a role in the maintenance of mice lung cancer stem cells; however, its function in human CSCs/CICs of EOC is still elusive." (PMID 27072580, 2016). "The role of MMP10 in maintenance and tumorigenicity of mouse lung cancer stem-like cells has been described." (PMID 24804215, 2014). "Our data demonstrate for the first time that Mmp10 is a critical lung cancer stem cell gene and novel therapeutic target for lung cancer stem cells." (PMID 22545096, 2012). "Here we reveal an unexpected role for Mmp10 (stromelysin 2) in the maintenance and tumorigenicity of mouse lung cancer stem-like cells (CSC)." (PMID 22545096, 2012). "Gene set enhancement analysis (GSEA) demonstrates that elevated MMP10 expression correlates with both cancer stem cell and tumor metastasis genomic signatures in human lung cancer." (PMID 22022614, 2011). "Here, we use a combination of mouse carcinogenesis models and analysis of human tumors to demonstrate that Mmp10 plays a novel, unexpected role in Kras-mediated lung cancer initiation, lung cancer stem cell expansion, and metastasis." (PMID 22022614, 2011). "Other studies have observed MMP10 upregulation in oesophageal carcinomas, recurrent lung carcinomas and in gliomas, where they predict a more malignant phenotype." (PMID 15928670, 2005). "Stromelysin-2, also known as matrix metalloproteinase-10 (MMP10), may mediate c-Fos driven cSCC development, and has been linked to lung cancer stem cell maintenance, tumor initiation and metastatic potential." (PMID 32674318, 2020). "Mmp10, the G9a target we characterized in lung cancer cells, directly mediates TPC tumorigenicity." (PMID 30455465, 2018). "In mouse lung cancer models Mmp10 was shown to be induced in bronchio-alveolar stem cells transformed by oncogenic KRas mutant and to promote KRas-mediated bronchio-alveolar stem cell expansion and lung cancer formation." (PMID 30060526, 2018). "On the basis of their lung-tumorigenesis promoting functions, the MMP members MMP-1, MMP-2, MMP-7, MMP-9 and MMP-10 may result promising biomarkers for lung cancer." (PMID 29207990, 2017).